G6PD (glucose-6-phosphate dehydrogenase)
Diseases named in the same sentence as G6PD in open-access papers (continued):
Sharing a sentence is not in itself a finding about the gene and the disease.
cancer (continued). "Indeed, loss of Snail decreased NADPH level, while gain of Snail function consistently increased NADPH level in a glucose-6-phosphate dehydrogenase (G6PD)-dependent manner, suggesting that Snail regulates NADPH homeostasis via PPP and thereby confers cancer cell survival against oxidative stress." (PMID 28176759, 2017). "More importantly, ID1/G6PD signaling was found to be a predictor of unfavourable clinical prognosis in HCC patients, suggesting that the ID1 signaling pathway may be a potential therapeutic target for inhibiting HCC progression and anti-cancer drug resistance." (PMID 29169374, 2017). "The aim of this hypothesis is to propose a new approach in targeted therapy of cancer: The simultaneous, dual targeting of two single molecules, Par-4 and G6PD, rather than inhibition of full-length signaling pathways." (PMID 27872579, 2016). "Given that IDH2 also performs catalytic actions on isocitric acid, by dehydrogenating it to form α-ketoglutarate and NADPH, we speculate that cancer cells may themselves provide more NADPH and TCA cycle intermediates to maintain hypoxia survivability through G6PD and IDH2 pathways." (PMID 26956544, 2016). "Nevertheless, there are biological limitations in explaining the relationship between cancer progression and G6PD activity measured in RBC, as opposed to G6PD activity within the cancer cells." (PMID 41514554, 2025). "How G6PD as a part of PPP affects cells, including cancer cell growth and death, has not been clearly defined." (PMID 31500396, 2019). "A recent study showed that PI3K/AKT activation increased the half-life of the G6PD protein through the inhibition of TRIM21-mediated ubiquitination, and the TRIM21 level had a negative correlation with PI3K/AKT activity in many human cancers." (PMID 37802999, 2023). "Despite accumulating evidence revealing that Glucose-6-phosphate dehydrogenase (G6PD) is highly expressed in many tumor tissues and plays a remarkable role in cancer tumorigenesis and progression, there is still a lack of G6PD pan-cancer analysis." (PMID 37601657, 2023).
tumor (350 papers, 1978 to 2026). "A few clinical observations similarly report enhanced tumor responsiveness in G6PD-deficient individuals, although the evidence is sparse and heterogeneous." (PMID 42123382, 2026). "In tumors with KRAS mutations, the expression level of G6PD is closely related to tumor progression and prognosis." (PMID 41328353, 2026). "This miRNA binds connexin-43 and can target glucose-6-phosphate dehydrogenase (G6PD), causing the inhibition of tumor cell proliferation and of tumor cell migration." (PMID 40141375, 2025). "Multiple studies have shown that the upregulation of G6PD is associated with tumor progression, increased aggressiveness, and drug resistance." (PMID 40533802, 2025). "Given G6PD's prominent role in lactate metabolism and its expression in key cell types linked to tumor progression, we selected G6PD for further functional validation." (PMID 40116585, 2025). "We focused specifically on G6PD because of its strong association with tumor progression and immune cell infiltration, as revealed in large‐scale transcriptomic datasets." (PMID 40116585, 2025). "Induction of G6PD expression in FOXO1-deficient cells mitigates tumor growth inhibition and alleviates ROS level elevation." (PMID 41124013, 2025). "As a key enzyme in the pentose phosphate pathway, G6PD is strongly implicated in tumor metabolism, oxidative stress regulation, and lactate metabolism." (PMID 40116585, 2025). "Recent studies have shown that G-6-PD is upregulated in various cancers and is associated with tumour progression and tumour chemotherapy resistance." (PMID 38288377, 2024). "Our investigation conducted at 12 weeks post-tumor induction, revealed that G6PD loss significantly impaired KL lung tumorigenesis, as evidenced by lower wet lung weight, reduced tumor number and tumor burden." (PMID 38997257, 2024). "Simultaneously, during tumor progression, G6PD-deficient cells increase serine uptake to maintain serine-driven one-carbon metabolism as an alternative NADPH source." (PMID 38997257, 2024). "The expression levels of G6PD were positively related to the tumor mutation burden, indicating that the group with high G6PD expression levels had a poor immunotherapy outcome and a poor prognosis, which was the same as the research result of Cao." (PMID 38297250, 2024). "As expected, G6PD deficiency significantly impeded allograft tumor growth in the vehicle control group." (PMID 38997257, 2024). "The ESTIMATE algorithms were used to analyze the association between G6PD expression and immune-infiltrating cells and the tumor microenvironment." (PMID 37601657, 2023). "An in vivo study also suggested that G6PD deficiency favored Escin-mediated inhibition of tumor growth." (PMID 37149513, 2023). "We transfected SK-BR-3 cells with the control vector or the vector encoding G6PD, and confirmed a lower level of autophagy in the presence of G6PD overexpression within tumor cells by fluorescence imaging observations." (PMID 38110365, 2023). "Enhanced G6PD activity has been linked to the upregulation of anti-apoptotic factors such as Bcl-2 and Bcl-xL, which contribute to promoting cell growth and tumor development." (PMID 37627157, 2023). "In all of these combinations, mice carrying a G6PD-Tg allele showed the same tumor latency and incidence as the WT mice." (PMID 36231003, 2022). "Subsequently, a prognostic risk score for all tumor samples was calculated using the formula: prognostic risk score = expression level of G6PD*(0.15) + expression level of CENPA*(0.075) + expression level of STC2*(0.018) + expression level of PFKFB4*(0.053)." (PMID 35938165, 2022). "To further explore the role of G6PD in the tumour immune microenvironment, we also analysed the association between G6PD and immune checkpoint molecules (PDCD1, CD274 and CTLA4)." (PMID 35712981, 2022). "All the tested signature genes were correlated with tumor grade, among which, G6PD was associated with T-stage." (PMID 36267406, 2022).
tumor (continued). "Considering these results, we concluded that TSP50 and G6PD expression is associated with hepatocyte proliferation and xenograft tumour formation." (PMID 33630390, 2021). "Early methods for assessing tumor clonality used X chromosome-linked studies such as: glucose 6 phosphate dehydrogenase (G6PD); phosphoglycerate kinase (PGK); and a human androgen receptor (HUMARA)." (PMID 32010429, 2020). "G6PD expression in the tumours of 105 OSCC patients was associated with lymphatic metastasis and prognosis." (PMID 32719549, 2020). "Histological scoring shows that elevated PAK4 and G6PD is significantly linked to poor pathological tumor–node metastases (pTNM)." (PMID 31500396, 2019). "Low expression levels of GPI and G6PD, which were unaltered in tumor compared with healthy tissue, have been associated with better patient survival." (PMID 30881919, 2019). "In contrast, increased activity of G6PD such as that observed in tumor cells, is typically linked with rapid cell proliferation." (PMID 31737625, 2019). "We also found that increased levels of G6PD mRNA were associated with a reduced patient outcome (Log-Rank P-value = 0.00015) and increased tumor recurrence (Log-Rank P-value = 0.0032)." (PMID 29904144, 2018). "A notable reduction in CD133, but not CK7 and Vimentin, expression was observed in G6pd knocked-down Ymac-1 tumor, which further supported the notion that G6pd is associated with CSC-like characteristics." (PMID 28596515, 2017). "In addition, OE of BANCR inhibited the growth of ccRCC cells in vivo, and G6PD was implicated in BANCR-mediated tumor suppression." (PMID 39894218, 2025). "A neoadjuvant approach utilizing G6PD inhibitors could reduce tumor size, improve surgical outcomes, and decrease the risk of metastasis." (PMID 39796677, 2024). "Thus, G6PD is likely to be particularly important in the context of specific tumor types or driver mutations." (PMID 38997257, 2024). "The GSEA results showed that the expression of G6PD was associated with metabolic-related activities, including ROS metabolism, carbohydrates, and glucose-6-phosphate on the one hand, and tumor immune responses including humoral immunity and cellular immunity on the other hand." (PMID 37601657, 2023). "The anti-tumour effects of Rec8 are caused by downregulation of cell growth-related genes (G6PD, SLC2A1, NOL3, MCM2, SNAI1, and SNAI2) and also by upregulation of both apoptosis or migration inhibitors (Gadd45G and LDHA) and tumour inhibitors (PinX1, IGFBP3, and ETS2)." (PMID 36139540, 2022). "Importantly, RIP140-deficient cells are more sensitive to G6PD inhibition in cell proliferation assays and tumor growth experiments." (PMID 35806424, 2022). "Moreover, in HCC samples, G6PD levels negatively correlate with miR-1 and the liver-specific miR-122, while loss of expression of these two miRNAs promotes tumor growth." (PMID 35348905, 2022). "In support of this, analysis of the TCGA PanCancer Atlas dataset, a very large dataset with transcriptomics on 494 primary tumor samples from 494 patients, revealed a significant association between high G6PD expression and a reduction in disease-free survival." (PMID 35213227, 2022). "In addition, the upregulation of G6PD has been reported to be associated with higher tumor grade, increased tumor recurrence, and poor survival in patients with HCC." (PMID 34819088, 2021).
tumor (continued). "To explore the effect of G6PD on tumour metastasis, we firstly investigated whether G6PD suppression was associated with cell migration and invasion." (PMID 32719549, 2020). "Remarkably, the translational value of the present results can be inferred by the observation that, similar to rat pre- and neoplastic lesions, in human HCCs high G6PD expression is associated with miR-1 down-regulation and correlates with tumor grading, metastatic status and poor prognosis." (PMID 27070090, 2016). "In contrast, G6PD-deficient tumor cell lines showed relatively slow growth and enhanced apoptosis." (PMID 24152564, 2013). "Linder had the idea of using G6PD isoenzymes to explore the question of the single cell origin (somatic mutation hypothesis) of neoplasms as contrasted with the field theory of carcinogenesis." (PMID 23908816, 2011). "Mutations in G6PD transcripts in tumour and nearby healthy tissues." (PMID 20186333, 2010). "Thus, increased G6PD expression in tumor cells can enhance their survival through the maintenance of redox homeostasis, which in turn aids in resisting various types of cell death, further underlining the significant role of G6PD in tumorigenesis." (PMID 38139067, 2023). "We also review the use of an X chromosome-linked gene product, glucose-6-phosphate dehydrogenase (G6PD), to further our understanding of gene dosage regulation, heterogeneity in the expression of X chromosome-linked traits, and as a tool to establish the single cell derivation of a neoplasm." (PMID 23908816, 2011). "In tumor cells, the G6PD enzyme product, 6PGL, and the 6PGD enzyme product, Ru5P have been reported to regulate the AMPK mediated signaling." (PMID 41535266, 2026). "Our findings support G6PD as a biomarker of tumor aggressiveness and G6PDi-1 as a potential therapeutic in RCC models." (PMID 41898704, 2026). "Functionally, co-targeting DLEU1 and ASCC2 synergized with G6PD inhibition, significantly impairing GC cells viability and tumor growth." (PMID 41484982, 2026). "Functionally, dual silencing of DLEU1 and ASCC2, in combination with G6PD inhibition, synergistically suppressed the viability of GC cells and tumor growth in vivo, highlighting the therapeutic potential of targeting the DLEU1/ASCC2/G6PD axis." (PMID 41484982, 2026). "Mechanistically, we identified FDPs regulate glucose-6-phosphate dehydrogenase (G6PD) by RNA sequencing, bioinformatics prediction, and rescue experiments, indicating its involvement in glycolysis regulation in tumour cells." (PMID 41667936, 2026). "Targeting the DLEU1/ASCC2/G6PD axis significantly suppresses GC cells proliferation and tumor growth, proposing a therapeutic strategy targeting this pathway." (PMID 41484982, 2026). "Given the ubiquitous and high basal expression of G6PD in both tumor and normal gastric tissues, establishing a clear regulatory link between E2F1 and G6PD in patient-derived samples is technically challenging." (PMID 41484982, 2026). "Tumor cells, often exposed to oxidative stress, rely on G6PD to generate NADPH, which is crucial for managing oxidative stress and supporting proliferation through the pentose phosphate pathway (PPP)." (PMID 39979245, 2025). "Hypoxic tumor microenvironments in HCC induce transcriptional upregulation of G6PD, which confers survival advantages through oxidative stress modulation." (PMID 41050691, 2025). "Immune infiltration analysis showed that G6PD expression positively correlated with CD8+ T cell infiltration in the tumor microenvironment." (PMID 40116585, 2025). "Despite numerous studies demonstrating the crucial role of G6PD in tumorigenesis, the specific molecular mechanisms governing its expression and activity regulation in tumor cells remain elusive." (PMID 39894218, 2025). "In vivo validation using subcutaneous xenografts model, G6PD knockdown reduced tumor volume and tumor weight compared to controls." (PMID 40685383, 2025).
tumor (continued). "Endogenous reductants such as NADPH and GSH produced by G6PD play an important role in determining the drug sensitivity of tumor cells under stress." (PMID 40685383, 2025). "Taken together, all these results suggest that metformin upregulates PER2, inhibits transplanted xenograft tumor growth in nude mice by inhibiting the SIRT2/G6PD signaling pathway and enhances radiotherapy sensitivity." (PMID 40166471, 2025). "Further research is needed to clarify the biological relationship between serum G6PD activity and tumor cell metabolism." (PMID 41514554, 2025). "The activity of Glucose-6-phosphate dehydrogenase (G6PD) is elevated in numerous tumor types, and studies have demonstrated that suppressing G6PD function can slow the progression of HCC." (PMID 40918463, 2025). "The TCGA LIHC dataset revealed that G6PD is significantly overexpressed in tumor tissues compared to normal tissues." (PMID 40116585, 2025). "Dimethyl fumarate (DMF), a glyceraldehyde-3-phosphate dehydrogenase (GAPDH) inhibitor, which has been shown to treat autoimmune diseases, was found to promote oxPPP by increasing G6PD expression in tumor cells." (PMID 39859324, 2025). "Our findings highlight the complex interplay between metabolic reprogramming and immune regulation, providing new perspectives on how metabolic enzymes like G6PD contribute to tumor immune evasion and therapeutic resistance." (PMID 40116585, 2025). "The specific mechanism is that FOXO1 transcriptionally activates G6PD to enhance the antioxidative capacity and, consequently, the anti-apoptotic and proliferative abilities of tumor cells in response to oxidative stress." (PMID 41124013, 2025). "By regulating the immune checkpoint PD‐L1, G6PD likely suppresses T cell activity, thus facilitating tumor growth and progression." (PMID 40116585, 2025). "In a subcutaneous xenograft model, the results confirmed that G6PD silencing synergized with sorafenib reducing tumor weight and tumor volume compared to sorafenib monotherapy." (PMID 40685383, 2025). "The targeted inhibition of G6PD increases tumor sensitivity to chemotherapy, particularly when the NRF2 pathway is activated, offering a potential strategy for anticancer therapy." (PMID 40299448, 2025). "Overexpression of glucose-6-phosphate dehydrogenase (G6PD) in GC is associated with oxidative stress adaptation and tumor aggressiveness, positioning it as a candidate prognostic biomarker." (PMID 41244835, 2025). "Studies have shown that LINC00242 promotes glycolysis and tumor cell proliferation via the miR-1-3p/G6PD axis." (PMID 41220952, 2025). "In IHC staining, we observed representative images of G6PD expression in HCC tumor samples and normal samples." (PMID 40307857, 2025). "Silencing LINC00242 significantly inhibits both proliferation and glycolysis, likely through competitive binding to miR-1-3p, which normally suppresses G6PD expression, thereby affecting tumor metabolism and growth." (PMID 41220952, 2025). "This consistency across datasets strengthens the evidence supporting G6PD and IK as potential biomarkers for tumor progression and promising therapeutic targets." (PMID 40116585, 2025). "Nevertheless, both NRF2 knockout and G6PD knockout HCC cell lines can't form tumor in xenograft model due to the essential roles of NRF2 and G6PD in cell grow and metabolism." (PMID 40963919, 2025). "BANCR and G6PD were mainly coexpressed and colocalized in the cytoplasm of cell lines and ccRCC tumor cells, which not only confirmed the ectopic expression of G6PD in ccRCC but also suggested a potential interaction between BANCR and G6PD." (PMID 39894218, 2025). "Knockdown of the lncRNA ELFN1-AS1 inhibits G6PD expression and thus tumor growth in mice transplanted into the body." (PMID 40859288, 2025).